DCX (doublecortin)
Diseases named in the same sentence as DCX in open-access papers (continued):
Sharing a sentence is not in itself a finding about the gene and the disease.
Lissencephaly (continued). "Mutations of the alpha tubulin 1A, LIS1 and doublecortin genes are all associated with classical forms of lissencephaly, with LIS1 and DCX mutations causing different malformation gradients along the fronto-occipital axis." (PMID 24782720, 2014). "The interaction between Usp9x and DCX is clearly important for human CNS development as patients with point mutations in DCX that cannot bind Usp9x, develop lissencephaly." (PMID 23861879, 2013). "USP9X is linked to lissencephaly, via its interaction with DCX, and USP9X is a candidate gene in X-linked intellectual disability and epilepsy." (PMID 23861879, 2013). "Mutations in doublecortin cause severe cortical malformations (doublecortex syndrome/lissencephaly) associated with intellectual disability and drug-resistant epilepsy." (PMID 23690918, 2013). "DCX has been identified as an important molecule in the proper lamination of the cortex, with mutations in the Dcx gene causing lissencephaly or double cortex syndrome in humans." (PMID 21966452, 2011). "The gene DCX located in Xq22 and encodes the Doublecortin protein, mutated in 40% of type I lissencephaly." (PMID 21569638, 2011). "Lissencephaly results from the failure of vertebrate cortical neurons to migrate properly during development, and is frequently caused by mutations in doublecortin (DCX)." (PMID 20300184, 2010). "Homo sapiens doublecortex; lissencephaly, X-linked (doublecortin) (DCX), transcript variant 1, mRNA." (PMID 19236693, 2009). "DCX mutations in human cause a spectrum of abnormalities ranging from type I lissencephaly to subcortical laminar heterotopia (SCLH), which are associated with mental retardation and epilepsy, the latter frequently refractory to treatment." (PMID 18575605, 2008). "Type I lissencephaly, due to DCX or LIS1 mutations, is associated with severe mental retardation and refractory epilepsy." (PMID 18575605, 2008). "Mutations in LIS1 and DCX account for approximately 85% patients with lissencephaly." (PMID 36769099, 2023). "Several diseases are linked to DCX variants such as Isolated Lissencephaly Sequence (ILS) which is a disorder characterized by abnormal brain development that results in the brain having a smooth surface (lissencephaly) instead of normal gyri and sulci." (PMID 35590332, 2022). "Furthermore, variants in DCX result in lissencephaly in males and subcortical laminar heterotopia in females." (PMID 31231230, 2019). "Additionally, DCX mutations are associated with lissencephaly in males and a subcortical band heterotopia pattern in females, since DCX is located on the X chromosome." (PMID 29628935, 2018). "Mutations in the human DCX gene, the first characterized gene of the family, result in abnormal neuronal migration, epilepsy, mental retardation and cause double cortex syndrome and lissencephaly in humans." (PMID 26331477, 2015). "Genetic counseling is particularly important for parents that have a boy with classical lissencephaly or a girl with subcortical band heterotopia because the mother may be a heterozygous carrier of the DCX mutation." (PMID 26052266, 2015). "For example, one of the key genes mutated in lissencephaly is doublecortin (DCX)." (PMID 20148114, 2010). "Interestingly, most missense mutations that are found in lissencephaly patients cluster in the defined DCX (doublecortin) domain." (PMID 16869982, 2006). "DCX, a microtubule-associated protein crucial for neuron migration and neocortical and hippocampal development, has been associated with significant developmental disorders in humans (lissencephaly) and mice (hippocampal lamination abnormalities), affecting learning and social behaviours." (PMID 39463206, 2024). "The psychomotor prognosis in LIS1/PAFAH1B1-related lissencephaly is significantly worse compared to DCX-related lissencephaly." (PMID 42177523, 2026).
Lissencephaly (continued). "The functions of certain lissencephaly genes, including LIS1, DCX, and TUBA1A, are closely associated with microtubules, which, as integral components of the cytoskeleton, play crucial roles in cellular processes such as mitosis and cytokinesis." (PMID 39857780, 2025). "Variants in PAFAH1B1/LIS1, DCX, and TUBA1A were recognized as key contributors to neuronal migration disorders, such as lissencephaly and subcortical band heterotopia, which frequently manifest with spasms in infancy." (PMID 41470225, 2025). "Somatic mosaicism of other lissencephaly genes, such as LIS1 and DCX, has previously been reported to cause SBH in addition to pachygyria." (PMID 38194050, 2024). "Genetic mutations of doublecortin (DCX) a DCLK1 homologue, were identified as the cause of cerebral cortical malformations, such as subcortical band heterotopia (double cortex) and lissencephaly." (PMID 36979969, 2023). "Regional severity has been noted in lissencephaly caused by mutations in LIS1, Lissencephaly 1, or DCX, Doublecortin." (PMID 35626679, 2022). "In humans, most cases of lissencephaly are caused by mutations in LIS1 and DCX genes, both of which code for proteins implicated in MT function." (PMID 36733270, 2022). "Differentiation of iPSCs into 2D neural cells provides a model system to further scrutinize the molecular and cellular regulation of Lissencephaly and in particular, the function of DCX in neurodevelopment." (PMID 36340790, 2022). "Mutations in the microtubule (MT)-binding protein doublecortin (DCX) or in the MT-based molecular motor dynein result in lissencephaly." (PMID 36476638, 2022). "In fact, patients carrying mutations in genes such LIS1, doublecortin (DCX), and cyclin-dependent kinase 5 (CDK5) show lissencephaly." (PMID 33659245, 2021). "More recent work has elucidated that cdk5/p35 is the mechanism through which the neuronal intermediate filament protein Nestin facilitates phosphorylation of the critical neuronal migration factor doublecortin (DCX), which is also linked to lissencephaly." (PMID 34888312, 2021). "Lissencephaly is caused by mutations in cytoskeletal genes such as PAFAHB1 and DCX." (PMID 35159273, 2022). "Another genetic cause associated with classic Lissencephaly, and SBH is mutations in the DCX gene." (PMID 36340790, 2022). "Germline DCX mutations in males and PAFAH1B1 in either sex result in lissencephaly." (PMID 28953922, 2017). "In principle, any perturbation to cortical migration could lead to lissencephaly phenotypes, but most identified cases are attributed to mutations to LIS1 (also known as PAFAH1B1), doublecortin/DCX, and more recently TUBA1A." (PMID 29057214, 2017). "Mutations or deletions in different genes have been identified as involved in lissencephaly cases: the LIS gene is responsible for the autosomal form of classical lissencephaly and the doublecortin gene (DCX or X-LIS) is X-linked whereas homozygous RELN gene has been identified in cases of LCH." (PMID 23938146, 2013). "Although the majority of patients with lissencephaly had a preserved normal-like appearance of major fissures and primary sulci, the spatial distribution of agyric cortical regions was different in patients with lissencephaly-1 (LIS1) and doublecortin (DCX) mutations." (PMID 31355197, 2019). "However, the strong genetic link between DCX and lissencephaly suggests that DCX may play a major role." (PMID 28232790, 2017). "Mutations of many genes are involved in neuronal migration disorders, such as LIS1 and DCX in classical lissencephaly spectrum, TUBA1A in microlissencephaly with agenesis of the corpus callosum, and RELN and VLDLR in lissencephaly with cerebellar hypoplasia." (PMID 26052266, 2015). "Histological examinations in TUBA1A mutated brains revealed structural abnormalities of the cortex, a fractured pyramidal layer of the hippocampus, and defects attributed to impairment of neuronal migration mechanisms, similar to the mouse models of lissencephaly (LIS1, DCX, RELN)." (PMID 31269740, 2019).
Lissencephaly (continued). "On the other hand, hemizygous mutations occur in male patients who possess no functional copy of the DCX protein resulting in lissencephaly." (PMID 28701917, 2017). "Patients with lissencephaly or SBH, but negative for DCX mutations, were subsequently studied for copy number variants." (PMID 28953922, 2017). "Absence of DCX resulted in migrational arrest and formation of the subcortical band heterotopia (“double cortex” syndrome) and lissencephaly (“smooth brain” syndrome)." (PMID 22038821, 2011). "In a recent summary of targeted sequencing studies for 17 genes in 811 patients with lissencephaly, a diagnostic rate of 81% was observed, in which > 99% of pathogenic variants were in LIS1, DCX, TUBA1A, or DYNC1H1, none of which are inherited in an autosomal recessive fashion." (PMID 33290415, 2020).
epilepsy (34 papers, 2006 to 2025). A brain disorder characterized by episodes of abnormally increased neuronal discharge resulting in transient episodes of sensory or motor neurological dysfunction, or psychic dysfunction. "In contrast, the chronic phase of epilepsy is often characterized by a reduction in DCX-positive cells in DG, which is associated with impairments in memory and cognitive function." (PMID 41516142, 2025). "DCX is an X-linked microtubule-associated protein; patients with DCX mutations have structural cortical malformations, often associated with epilepsy." (PMID 40529445, 2025). "Mutations in human DCX have been identified as being causative in double cortex syndrome and other cortical malformations associated with epilepsy." (PMID 34831225, 2021). "One of the gene found to be linked to epilepsy is DCX, the gene coding for the doublecortin protein." (PMID 28933765, 2017). "For example, doublecortin is associated with band heterotopia, a condition with severe intellectual disability and epilepsy, and which has been shown to be a consequence of radial migration deficits during neocortex development." (PMID 25162227, 2014). "Mutations in DCX genes result in abnormal neuronal migration, epilepsy, mental retardation, inherited blindness, and dyslectic reading disabilities." (PMID 21647313, 2011). "Mutations in the human DCX gene result in abnormal neuronal migration, epilepsy, and mental retardation; mutations in RP1 are associated with a form of inherited blindness, and DCDC2 has been associated with dyslectic reading disabilities." (PMID 16869982, 2006). "Given that LIS1 and DCX genes are implicated in radial and tangential migration in the cortex, the origin of epilepsy condition in humans with mutations in these genes remains unclear." (PMID 36733270, 2022). "DCX mutations may also course with intellectual disability and/or epilepsy giving raise to subcortical band heterotopia in females and also occasionally in males." (PMID 24782720, 2014). "Tubulin genes play a key role in several pathways of cortical development such as other genes encoding microtubule-related proteins (i.e., Lissencephaly 1, Doublecortin, Filamin A or Reelin genes) and when mutated, may cause specific brain malformations strictly associated with epilepsy." (PMID 31269740, 2019). "We also identified a subset of ramified and small cells with DCX antibodies, representing a range of glial cell types and supporting non-neuronal DCX expression; these were increased in number in the neocortex in epilepsy, associated with memory impairment and may represent reactive populations." (PMID 30005693, 2018). "DCX + cells were also found in these cortices in pediatric epilepsy surgical samples and DCX + and PSA-NCAM + cells have been recently described in the parahippocampal gyrus of humans of different ages." (PMID 35464133, 2022). "At the chronic stage of epilepsy, the number of hippocampal DCX-positive cells in the EP group was significantly reduced compared with the SHAM group (3.0 ± 0.4 vs. 17.3 ± 2.0, respectively; P < 0.05)." (PMID 34979964, 2022). "We also found that DL-NBP significantly increased the number of hippocampal DCX-positive cells in the chronic stage of epilepsy." (PMID 34979964, 2022). "DCX is related to neuron migration, and the expression of DCX in the lesion area of patients with tuberous sclerosis is higher than the normal control, which may be related to abnormal neuronal localization (heterotopia), intellectual disability and epilepsy caused by DCX." (PMID 32655475, 2020). "DCX-expressing astroglial cells have been noted in adult post mortem tissues in patients with epilepsy and controls, in balloon cells in FCD IIB and multipolar astroglial like cells in temporal lobe sclerosis." (PMID 30005693, 2018).
epilepsy (continued). "We compared this to findings in post-mortem (PM) samples from patients with epilepsy and HS and non-epilepsy controls to explore any differences in the morphology and number of DCX + cells between these groups." (PMID 30005693, 2018). "We observed DCX+ reactive glial cell types, including microglial lineages with some evidence for increased numbers in epilepsy tissue." (PMID 30005693, 2018). "Significantly more ramified DCX+ cells were noted in surgical epilepsy cases in the temporal cortex compared to controls." (PMID 30005693, 2018). "Under pathophysiological conditions, such as in epilepsy, the expression patterns of DCX are altered and DCX+ cells have been observed in distinct cortical areas." (PMID 25881110, 2015). "Regarding the morphological changes affecting the apical dendrites of newborn neurons, doublecortin (DCX)-expressing neuroblasts undergo changes in the pilocarpine model of epilepsy." (PMID 26834550, 2015). "For example, both familial (inherited) and acquired (‘de novo’, somatic variants) of doublecortin cause subcortical band heterotopia (SBH), a neuronal migration syndrome that results in epilepsy and intellectual disability." (PMID 25254102, 2014). "Double-labelling immunofluorescent studies further demonstrated the co-localisation of pS6 with nestin, doublecortin, GFAPdelta in populations of small, immature neuroglial cells in a range of epilepsy pathologies." (PMID 25005575, 2014). "Patients with Doublecortin (DCX) mutations have severe cortical malformations associated with mental retardation and epilepsy." (PMID 18575605, 2008). "DCX expressing cells with ramified processes were prominent in all regions, particularly in the hippocampal subgranular zone, where significantly increased numbers were observed in epilepsy samples compared to controls." (PMID 30005693, 2018). "In the temporal lobe we confirmed higher linear densities for all morphological DCX+ cell types in surgical epilepsy cases compared to PM epilepsy cases and non-epilepsy controls with statistically significant differences noted for ramified DCX+ cell populations (p < 0.0001)." (PMID 30005693, 2018). "In addition, we compared the histo- and physio-pathological features of our model with a genetic epilepsy-prone model of hippocampal malformation, the doublecortin (Dcx) knockout mouse." (PMID 24782720, 2014). "These different observations suggest enhanced DCX expression in reactive glial cells types in epilepsy could be independent of underlying pathology." (PMID 30005693, 2018). "Here, we focus on reelin (RELN) and doublecortin (DCX), whose functions with respect to neural migration and epilepsy are more elucidated." (PMID 40529445, 2025). "The higher numbers of DCX+ and CR+ granular cells detected at the III–IV AD stages have also been reported in other neuropathologies such as epilepsy, schizophrenia, and Creutzfeld–Jacobs disease." (PMID 36361662, 2022). "DCX immunohistochemistry identified immature (Nestin−/NeuN−) neurons in layer II of the temporal neocortex in patients with and without epilepsy." (PMID 30005693, 2018). "In agreement with a previous report, we found that DCX-positive cells were almost absent from the dentate granule cells of aged controls and aged rats with late epilepsy onset." (PMID 23898322, 2013). "The aim of the present study was to explore the distribution and characteristics of DCX-expressing cells in surgical and postmortem samples from 40 adult and paediatric patients, with epilepsy and with or without hippocampal sclerosis (HS), compared to post mortem controls." (PMID 30005693, 2018).
epilepsy (continued). "DCX identifies a range of morphological cell types in temporal lobe epilepsy, including immature populations in the superficial cortex and amygdala that decline with age but may not be specifically relevant to the epilepsy or local pathology." (PMID 30005693, 2018).